MAPKAPK2 (MAPK activated protein kinase 2)
Diseases named in the same sentence as MAPKAPK2 in open-access papers (continued):
Sharing a sentence is not in itself a finding about the gene and the disease.
tumor (38 papers, 2012 to 2025). "MAPKAPK2 also functions in tumor-associated macrophage polarization and promotes the macrophages into pro-tumorigenic M2-like macrophages to promote tumor progression in the colorectal cancer model." (PMID 38322416, 2024). "In summary, although the tumor suppressive role of MAPKAPK2 remains elusive, our results have implicated miR-96-5p/MAPKAPK2 as a promising therapeutic target for reducing the chemoresistance in AA PCa." (PMID 35328346, 2022). "Activated p38 MAPK can phosphorylate and activate MAPKAPK2 and is associated with tumor initiation and development." (PMID 31354723, 2019). "In order to unearth the potential roles of MAPKAPK2 in tumor progression, we firstly analyzed its expression in 33 types of human cancers and the corresponding normal tissues from TCGA." (PMID 38322416, 2024). "According to recent studies, HSPB1 can form a p38/pMAPKAPK2/pHSPB1 cascade with p38/MAPKAPK2 in GC to encourage tumor growth and metastasis." (PMID 37016377, 2023). "Three model features correlated with clinical outcomes in an independent cohort: granulocyte MAPKAPK2 signaling at the tumor front, stromal CD4+ memory T cell size, and the distance of fibroblasts from the tumor border." (PMID 38125025, 2023). "To dissect the dynamic changes of both kinases and phosphoproteins in PDAC, we performed kinase–substrate enrichment analysis (KSEA), and four kinases (HIPK2, ROCK1, PRKCD, MAPKAPK2) were identified as tumor-specific activated." (PMID 36434634, 2022). "Many studies have shown that METTL3 promotes tumor growth and aggressiveness by regulating the mRNA decay and stability or mRNA translation of numerous tumor-associated genes, such as SOCS2, BATF2, EGFR, TAZ, MAPKAPK2, and DNMT3A." (PMID 35456475, 2022). "Previous studies have shown that p38 MAPK has a dual role as a tumor suppressor kinase or a tumor promoter, however, the diverse functional roles of MAPKAPK2 remain elusive." (PMID 35328346, 2022). "MAPKAPK2 has been confirmed as the core regulator of RNA-binding proteins and has the ability to sustain regulation stability and inhibition of tumor progression." (PMID 36761693, 2022). "The bioinformatics analysis showed that the expression levels of DTYMK and MAPKAPK2 highly correlated in various tumor types, and they shared the same binding site on miR-378a-3p." (PMID 34795209, 2021). "Among these genes, four genes (TIMP1, MAPK13, MAPKAPK2 and MAPKAPK3) are known to regulate cell proliferation, and MMP2 and MMP9 control tumour-associated tissue remodelling; PIK3CD is involved in the immune response, and AKT2 regulates tumourigenesis." (PMID 32999349, 2020). "Significance of p38/MAPKAPK2 (Mitogen-activated protein kinase-activated protein kinase-2) pathway in cell stress and inflammation is well established and its role in tumor development is being widely studied." (PMID 31023373, 2019). "Tumour-resident DCs exhibited pronounced upregulation of Mapkapk2 by 1.9-fold as compared to splenic DCs and also expressed high levels of Il10, Tgfb1 and Arg1, suggesting robust immunosuppressive activity of these cells within the TME." (PMID 28924177, 2017). "RT-qPCR analysis revealed elevated expression of Mapkapk2 in all tumour-resident myeloid subsets compared to the corresponding splenic populations." (PMID 28924177, 2017). "pHSP27 can bind to AKT and act as a scaffold protein to permit the phosphorylation of AKT by MAPKAPK2, leading to enhanced tumor cell survival signaling by mTOR activation and downstream suppression of autophagy." (PMID 22480225, 2012). "Interestingly, the mTOR/MAPKAPK2/4EBP1/ZFP36L1 axis blunts both the pro-tumorigenic the tumour-suppressive effects of the SASP." (PMID 38317146, 2024). "MAPKAPK2 was enriched in microglia/macrophages and malignant tumor cells." (PMID 38322416, 2024).
tumor (continued). "MAPKAPK2, a key p38 downstream substrate involved in cell cycle control, DNA repair, immune response, senescence, and autophagy, may also function as a cofactor in the p38-mediated tumor suppressor pathways." (PMID 35328346, 2022). "MAPK-activated protein kinase 2 (MAPKAPK2) is a serine/threonine kinase, which is involved in tumorigenesis, tumor growth, metastasis, and the inflammatory process." (PMID 38322416, 2024). "In another study, a primary tumor from a bitransgenic KrasG12C mouse observed the phosphorylation of RAS-downstream effector factors: ERK, p38, p90 ribosomal S6 kinase (RSK), and MAP kinase-active protein kinase 2 (MAPKAPK-2)." (PMID 39056802, 2024). "MAPKAPK2, MAOA, and EPHX2 were demonstrated to affect tumour development in various contexts." (PMID 36826154, 2023). "A recent work demonstrated for the first time, using a mouse model of IBD-CRC, that the M2 macrophage polarization could be altered by genetic inactivation of the MAPK-activated protein kinase 2 (MK2), resulting in delayed tumor progression." (PMID 34744751, 2021). "Here we describe a novel role for members of the stress-activated protein kinase (p38 MAPK) signaling pathway, MAPKAPK2 (MK2) and MAPKAPK3 (MK3), in mediating Beclin 1 S90 phosphorylation, which we show is essential for its autophagy and tumor suppressor function." (PMID 25693418, 2015). "The biological function of MAPKAPK2 in tumor has not been well elucidated." (PMID 38322416, 2024). "In addition, DTYMK could competitively combine with miR-378a-3p to maintain the expression of MAPKAPK2 and thus activate the phospho-HSP27/NF-κB axis, which mediated drug resistance, proliferation of tumor cells, and infiltration of CD163+ M2-type TAMs by inducing the expression of CCL5." (PMID 34795209, 2021). "The kinases MAPKAPK2, RPS6KB1 and RPS6KA3 were more often regulated in the noncancer conditions when compared to their degree of regulation in tumours." (PMID 36688815, 2023).
cancer (28 papers, 2012 to 2025). A tumor composed of atypical neoplastic, often pleomorphic cells that invade other tissues. "Additionally, mutations in JAK1 and MAPKAPK2 have been associated with various types of cancer, but their relationship with CTRP6 expression remains to be fully explored." (PMID 39979869, 2025). "We focused on three genes that are associated with cancer: MAPKAPK2, ATF4, and BCL2." (PMID 36142475, 2022). "Several studies revealed that MAPKAPK2 facilitated progression of diverse cancers by promoting the proliferation, evasion, apoptosis induction, angiogenesis, or chemotherapy/radiotherapy resistance." (PMID 38322416, 2024). "Apart from that, the translational activation of MAPKAPK2 in cancer cells after GRO-NLs exposure suggests its putative role in the phosphorylation of Cdc25C at Ser216, which assists in the cytoplasmic degradation, inactivation, and growth inhibition of cells." (PMID 37298090, 2023). "In our study, the fraction of water eluate results in p38 activation as indicated by MAPKAPK2 phosphorylation, and functional analysis shows concomitant p38 inhibition exacerbates the suppressive effects of water eluate on cancer cells growth." (PMID 31777585, 2019). "Another possible conjunction of vitamin D and progressive disease might be due to low expression of MAPKAPK2, which is already known to play a role in cancer invasion." (PMID 37114140, 2023). "In the present study, the p38/MAPKAPK2 pathway is activated by hypoxia in A549 cancer cells." (PMID 30634531, 2019). "Hsp27 involvement in cancer could be through phosphorylation at three-serine residues mediated by MAPKAPK2 (mitogen-activated protein kinase activated protein kinase)." (PMID 29295496, 2017). "Surprisingly, resistomycin treatment dose-dependently upregulated the expression of phosphor-p38 and phosphor-MAPKAPK-2 but expression of p38 remained unchanged, suggesting the possibility that p38 MAPK may be associated with the anti-cancer activities of resistomycin." (PMID 34681182, 2021). "Consequently, TGF-β1/MKK3/6/p38/MAPKAPK2/HSP27 forms a signaling axis involved in cancer promotion." (PMID 27806310, 2016). "We aimed to understand how MAPKAPK2 (MK2) regulates HNSCC tumor cell migration and invasion, important first steps in cancer metastases." (PMID 40185303, 2025). "MAPK-activated protein kinase 2 (MAPKAPK2 or MK2) is activated via p38 MAPK-mediated phosphorylation in response to stress and exhibits diverse roles in inflammation and cancer." (PMID 32168910, 2020). "MAPKAPK2 (MK2), the direct substrate of p38 MAPK, has been well-acknowledged as an attractive drug target for cancer therapy." (PMID 31440466, 2019). "Therefore, the differentially methylated specific genes (NTRK2, MAPKAPK2, CRK, and NFATC2) and the dysregulated miRNAs (mir-148a, mir-374a and mir-494) in the MAPK and ErbB pathways cause cell proliferation, adhesions and migration and the immune cell infiltration to cancer cells during early HCC." (PMID 27821810, 2016). "Some roles described for the physiological functions of the cell are exploited by cancer cells to their advantage to allow the self-renewal of the cancer stem cells, to increase translation of oncogenes such as EGFR, MYC, TAZ, MAPKAPK2 and to use shelter systems to allow cell survival." (PMID 34530916, 2021). "MAP2K4, and MAPKAPK2 belong to the MAPK family, which is involved in cell proliferation, differentiation, and apoptosis, while CDC25B plays an important role in cell cycle, and is deregulated in several types of cancer." (PMID 27821810, 2016).
infection (7 papers, 2018 to 2025). The state of being infected such as from the introduction of a foreign agent such as serum, vaccine, antigenic substance or organism. "Moreover, kinases found to be upregulated by the infection of HIBCPP cells with both N. meningitidis strains in this analysis (downregulated in control cells) include MAPKAPK2, RPS6KB1, RET as well as AKT1 and AKT2, whereas PRKACA activity was upregulated only by MC58siaD." (PMID 37065199, 2023). "The molecular target of these molecules is MK2 (MAPK-activated protein kinase 2) and its limited expression, which results in inhibition of the MAPK pathway activation and the spread of infection." (PMID 37511254, 2023). "In NHBE and THP-1 cells, five mitogen-activated protein kinase (MAPK) family members (MAP2K3, MAP2K6, MAPKAPK2, MAPKAPK3, MAPKAPK5) showed decreased activity or no significant change during pH1N1 infection, and increased activity during H3N2 and H5N1 infection." (PMID 37758692, 2023).
MAPKAPK2 also shares sentences with these, for which no sentence is quoted: non-small cell lung carcinoma (2 papers); Parkinson disease (2); adenovirus infection (1); aspergillosis (1); atherosclerosis (1); bacterial infection (1); breast tumor (1); cervical squamous cell carcinoma (1); clear cell renal cell carcinomas (1); cryptosporidiosis (1); head and neck cancer (1); heart failure (1); hemangioma (1); Hypertension (1); influenza (1); Kaposi's sarcoma (1); lung adenocarcinoma (1); medulloblastoma (1); melanoma (1); metabolic disease (1); multiple sclerosis (1); nasopharyngeal carcinoma (1); oligoastrocytoma (1); oligodendroglioma (1); oral cancer (1); osteoporosis (1); ovarian carcinoma (1); pancreatic adenocarcinoma (1); renal cell carcinoma (1); thyroid carcinoma (1).
A further 4 diseases each share a sentence with MAPKAPK2 in 1 paper.